CDK5RAP1 (CDK5RAP1 mitochondrial tRNA methylthiotransferase)
Description:
Methylthiotransferase that catalyzes the conversion of N6- (dimethylallyl)adenosine (i(6)A) to 2-methylthio-N6- (dimethylallyl)adenosine (ms(2)i(6)A) at position 37 (adjacent to the 3'-end of the anticodon) of four mitochondrial DNA-encoded tRNAs (Ser(UCN), Phe, Tyr and Trp). Essential for efficient and highly accurate protein translation by the ribosome. Specifically inhibits CDK5 activation by CDK5R1. Essential for efficient mitochondrial protein synthesis and respiratory chain; shows pathological consequences in mitochondrial disease.
Synonyms: C20orf34; CGI-05; HSPC167; C42
Tractability: PROTAC: ubiquitination databases record sites on it.
Gene: Protein-coding gene on chromosome 20 (33,358,437 to 33,401,561, reverse strand). Ensembl gene ENSG00000101391.
Subcellular location: Mitochondrion
Subcellular location (Human Protein Atlas): Mitochondria; Cytosol; Nucleoplasm
Gene Ontology:
Molecular function: tRNA-2-methylthio-N(6)-dimethylallyladenosine(37) synthase activity; protein kinase binding; 4 iron, 4 sulfur cluster binding; catalytic activity; iron-sulfur cluster binding; methylthiotransferase activity; transferase activity
Biological process: negative regulation of cyclin-dependent protein serine/threonine kinase activity; RNA modification; brain development; mitochondrial tRNA modification; negative regulation of cell cycle; regulation of neuron differentiation; regulation of protein metabolic process; tRNA methylthiolation; tRNA modification
Cellular component: cytosol; mitochondrial matrix; mitochondrion; nucleoplasm
Genetic constraint (gnomAD): Loss-of-function variants: 34 observed, 41.92 expected, observed/expected ratio (o/e) 0.81, 90% interval 0.62 to 1.08. The upper end of that interval is the gene's LOEUF score, 1.08, which puts it in group 4 of 6, group 1 being the genes least tolerant of losing a copy. Missense variants: 513 observed, 612.82 expected, observed/expected ratio (o/e) 0.84, 90% interval 0.78 to 0.9. Synonymous variants: 208 observed, 221.33 expected, observed/expected ratio (o/e) 0.94, 90% interval 0.84 to 1.05.
Homologues: Orthologues: chimpanzee CDK5RAP1 (99% identical), macaque CDK5RAP1 (97% identical), dog CDK5RAP1 (90% identical), pig CDK5RAP1 (90% identical), guinea pig CDK5RAP1 (89% identical), mouse Cdk5rap1 (88% identical), rabbit CDK5RAP1 (87% identical), rat Cdk5rap1 (86% identical). Paralogues in human: CDKAL1 (22% identical).
Diseases named in the same sentence as CDK5RAP1 in open-access papers:
CDK5RAP1 is named in the same sentence as 21 diseases in open-access papers, as found by Europe PMC text mining. Sharing a sentence is not in itself a finding about the gene and the disease. The quoted sentences say what the papers report.
breast carcinoma (4 papers, 2018 to 2024). "On one hand, it is documented that repression of CDK5RAP1, an inhibitor of cyclin-dependent kinase 5 activity, forces malignant melanoma and human breast cancer cell lines to undergo apoptosis." (PMID 38276004, 2024). "In human breast cancer MCF-7 cells, CDK5RAP1 deficiency induces cell cycle arrest and apoptosis indicating an antiapoptotic function of this protein." (PMID 34257800, 2021). "In breast cancer cells MCF-7 Cdk5rap1 paucity induces cell cycle arrest." (PMID 29875623, 2018). "CDK5RAP1 was hypothesized as having a role in human breast cancer growth." (PMID 33061813, 2020).
malignant melanoma (3 papers, 2012 to 2024). "Of the 19 type-specific mutated genes, CDK8 has been established as a colorectal cancer oncogene that regulates beta-catenin activity and CDK5RAP1 located on the melanoma-susceptibility region." (PMID 22691569, 2012). "CDK5RAP1 deficiency was also found to induce apoptosis in melanoma A375 cells via the NF‐κB signaling pathway 57, indicating that different tumors might have and share similar pathways related to their development." (PMID 33061813, 2020).
age-related hearing loss (1 paper, 2023). "Previous studies have revealed that age-related hearing loss (AHL) in Cdk5 regulatory subunit-associated protein 1 (Cdk5rap1)-knockout mice is associated with pathology in the cochlea." (PMID 37258461, 2023).
Alzheimer disease (1 paper, 2025). A progressive, neurodegenerative disease characterized by loss of function and death of nerve cells in several areas of the brain leading to loss of cognitive function such as memory and language.
Pain (1 paper, 2022). An unpleasant sensory and emotional experience associated with actual or potential tissue damage, or described in terms of such damage. "Zhang and colleagues demonstrated that spinal piRNA-DQ541777 (piR-DQ541777) was significantly increased in mice subjected to CCI-induced neuropathic pain which indirectly, via recruiting DNMT3a, repressed the expression of CDK5 regulatory subunit-associated protein 1 (Cdk5rap1)." (PMID 35054943, 2022).
Parkinson’s (1 paper, 2018). "CDK5RAP1 is a repressor of CDK5, which is a cyclin-dependent protein known to be involved in neurodegenerative diseases like Parkinson’s and Alzheimer’s." (PMID 30096876, 2018).
vitiligo (1 paper, 2022). Generalized well circumscribed patches of leukoderma that are generally distributed over symmetric body locations and is due to autoimmune destruction of melanocytes. "Based on our prioritization pathway, we found that genetic variants of FGFR10P, SUOX, CDK5RAP1 and RERE have the potential to directly or indirectly contribute to the disease pathogenesis, suggesting that hitherto unexplored biological pathways may be involved in imparting vitiligo risk." (PMID 36008553, 2022). "Our analysis revealed genes like FGFR10P, SUOX, CDK5RAP1 and RERE that have never been implicated in vitiligo previously to have strong potentials to contribute to the disease pathogenesis." (PMID 36008553, 2022). "On the contrary, CDK5RAP1 and RERE have neither been previously implicated in vitiligo and/or pigmentation or were found to interact with known vitiligo related genes or any of the other prioritized genes." (PMID 36008553, 2022).
tumor (5 papers, 2012 to 2024). "The mitochondrial methyl-thio-modifying enzyme, Cdk5 regulatory subunit-associated protein 1 (CDK5RAP1), plays a crucial role in maintaining the tumor-propagating capacity and self-renewal capacity of GSCs." (PMID 38476632, 2024). "To find tumor-associated genetic and epigenetic changes in the A37-modifying enzymes TRIT1 and CDK5RAP1, we data-mined a collection of about 1000 human cancer cell lines in which the transcriptome, DNA methylation landscape, exome sequence, and gene copy number were available." (PMID 33919717, 2021).
cancer (3 papers, 2005 to 2021). A tumor composed of atypical neoplastic, often pleomorphic cells that invade other tissues. "However, cancer cell apoptosis genes such as CDK5RAP1 and BCL2 or iron-sulfur clusters, which protects cancer cells against oxygen to damage a class of iron-dependent proteins such as NSF1, are significantly higher in the “CD74 low” samples." (PMID 33327409, 2020).
myopathy (3 papers, 2018 to 2025). A disease of the muscle in which the muscle fibers do not function properly. "In mice, deletion of the enzyme responsible for 2-methylthio modifications, Cdk5rap1, impairs mitochondrial protein translation and leads to myopathy." (PMID 41155428, 2025). "Analysis of CDK5RAP1 function in CDK5RAP1 knockout mice revealed impaired mitochondrial integrity and protein synthesis as well as accelerated myopathy and cardiac dysfunction in stress conditions." (PMID 28752201, 2018). "Indeed, CDK5RAP1 KO is more likely to determine stress-induced mitochondrial remodeling and exhibit accelerated myopathy and cardiac dysfunction." (PMID 33061813, 2020).
CDK5RAP1 also shares sentences with these, for which no sentence is quoted: colorectal cancer (1 paper); glioblastoma (1); glioma (1); infection (1); lactic acidosis (1); Mitochondrial encephalopathy (1); neurodegenerative disease (1); oral cancer (1); Sepsis (1); Stroke (1); systemic inflammatory response syndrome (1).